SP1 (Sp1 transcription factor)
Diseases named in the same sentence as SP1 in open-access papers (continued):
Sharing a sentence is not in itself a finding about the gene and the disease.
esophageal cancer (9 papers, 2014 to 2025). A primary or metastatic malignant neoplasm involving the esophagus. "It is also confirmed that HIF-1α has a direct regulatory effect on the transcription of SP1 in esophageal cancer." (PMID 31892989, 2020). "In summary, this study has found that HIF-1α and SP1 are highly expressed in esophageal cancer tissues and the expression levels of these two are positively correlated." (PMID 31892989, 2020). "There was a positive correlation between the expression of HIF-1α and SP1 in esophageal cancer tissues (R=0.5388 P <0.0001)." (PMID 31892989, 2020). "In addition, HIF-1α, bound to the SP1 promoter, regulated SP1 transcription, thereby inducing changes in migration and invasion abilities of esophageal cancer cells." (PMID 31892989, 2020). "The role of SP1 in HIF-1α-regulated migration and invasion of esophageal cancer cells were then investigated using complementation assays." (PMID 31892989, 2020). "In conclusion, our results suggested that miR-145-5p plays tumor-suppressive roles by inhibiting esophageal cancer cell migration, invasion and EMT through regulating the Sp1/NF-κB signaling pathway." (PMID 28832500, 2017).
HIV-1 infection (9 papers, 2011 to 2025). The type species of lentivirus and the etiologic agent of acquired immunodeficiency syndrome (AIDS). "Sp1’s highly integral role in promoter activation places it at the forefront of involvement with many cell types susceptible to HIV-1 infection (T cells, monocytes/macrophages, iDC, and microglia)." (PMID 40143226, 2025). "During HIV-1 infection, Tat promotes Sp1 phosphorylation via the protein kinase DNA-activated catalytic subunit (PRKDC), contributing to viral expression from the LTR." (PMID 40143226, 2025). "The interaction of Tat with host factors, such as specificity protein 1 (Sp1), is crucial in regulating both viral and host gene expression and underscores its importance in the pathogenesis of HIV-1 infection." (PMID 37298569, 2023). "These structures provide a blueprint for future development of small molecule inhibitors that can lock SP1 in a stable helical conformation, interfere with virus maturation, and thus block HIV-1 infection." (PMID 33863979, 2021). "Based on these interesting findings, it will be necessary to focus specifically on the transcriptional factors (NF-κB and SP1) and pro-apoptotic genes (bcl-2) in future research on bDLE as an antiviral against HIV-1 infection." (PMID 22044844, 2011). "TRIM22 inhibits basic HIV-1 transcription by preventing Sp1 from binding to the HIV-1 promoter, thus inhibiting HIV-1 infection." (PMID 36587218, 2022). "Also, it was reported that Sp1 and GABP factors cooperates to activate various genes such as CD18 which overexpression during HIV-1 infection has been related to disease severity." (PMID 29664930, 2018).
renal cell carcinoma (9 papers, 2019 to 2025). "LicoA was also found to suppress cell survival, cause cell cycle arrest, and inhibit the motility of invasive cells by modulating the FAK/Src-mediated expression of Sp1 in renal cell carcinoma (RCC)." (PMID 40002335, 2025). "In renal cell carcinomas, SNHG12 was involved in the regulation of the CDCA3 (cell division cycle associated 3) gene mediated by SP1, promoting resistance to sunitinib." (PMID 35406435, 2022). "SP-1 induces both the intrinsic and the extrinsic apoptotic pathways in human renal cell carcinoma and chronic myeloid leukemia through the reduction in NF-κB." (PMID 34572295, 2021). "SP1-induced up-regulation of lncRNA SNHG14 was demonstrated to promote the metastatic potential of cell renal cell carcinoma cells." (PMID 32396871, 2020). "SP-1 suppressed the phosphoinositide 3-kinases (PI3K)/AKT pathway and the MAPK family member ERK in human renal cell carcinoma." (PMID 34572295, 2021).
Stroke (9 papers, 2014 to 2024). Sudden impairment of blood flow to a part of the brain due to occlusion or rupture of an artery to the brain. "In agreement with our findings, transcriptomic analysis of astrocytes has shown Stat3, Sp1, and Spi1 as the most significant transcription factors in stroke." (PMID 35250546, 2022). "In another pathway, SP1 → IL10 → stroke, SP1 positively regulates the transcription of IL10, which has been successfully used as a therapeutic mediator to reduce post-stroke secondary neuroin-flammation." (PMID 33092540, 2020). "Among the 24 DVT-specific genes, one DVT-inhibiting gene, SP1, presented significantly increased expression in stroke (LFC = 1.34, p-value = 0.0045)." (PMID 33092540, 2020). "As a result, altered SP1 transcriptional activity leads to promoted production of leptin, which ameliorates neurological deficits and reduces infarct volumes after stroke." (PMID 33092540, 2020). "Prdx6 upregulation by Cur treatment attenuates ischemic oxidative damage through SP1 induction in rats after stroke." (PMID 28596967, 2017). "The findings from MitA inhibition and Sp1-regulated ETBR vasoconstriction of rat MCAs in vitro were then validated in experimental stroke." (PMID 25479176, 2014). "Activation of NK cells in a SP1-dependent manner may provide a novel target for preventing post-stroke infection." (PMID 38384585, 2024). "In addition, sp1 is involved in the pathogenesis of cerebral edema after stroke by regulating Ca-ATP ion channels." (PMID 38377019, 2024). "The pathways indicated two potential mechanisms that SP1 may play a protective role against the development of stroke: 1) SP1 promotes stroke-inhibitors (highlighted by green); 2) SP1 inhibits stroke-promoters (highlighted by red)." (PMID 33092540, 2020). "Although sample size, sample age, and sample organism of 11 datasets were used in the mega-analysis, the population region (country) was the only factor that could affect the expression of SP1 in case of stroke (p = 0.037)." (PMID 33092540, 2020). "Pathway analysis showed that SP1 may play a therapeutic role in post-stroke patients by promoting multiple of stroke-inhibitors." (PMID 33092540, 2020). "Specifically, SP1 presented significant increased LFC in case of stroke in mega-analysis." (PMID 33092540, 2020). "Our results suggested that DVT inhibitor SP1 could be a novel therapeutic target gene for post-stroke treatment." (PMID 33092540, 2020). "Enhanced activity of SP1 may contribute to the therapeutic effect in post-stroke patients by promoting multiple of stroke inhibitors." (PMID 33092540, 2020). "In specialty, LFC of SP1 was 1.34 from mega-analysis, demonstrating the changes of SP1 were increased by more than 150%, suggesting it was a potential stroke biomarker and maybe possibly involved in the development of stroke." (PMID 33092540, 2020). "Moreover, geographical region was indicated as an influential factor on the expression levels of SP1 in stroke samples (p-value = 0.037)." (PMID 33092540, 2020). "Further study of the potential relations between SP1 and stroke was guaranteed." (PMID 33092540, 2020). "Our hypothesis is that Cur exerts neuroprotective effects through activation of Prdx6/SP1 during a stroke." (PMID 28596967, 2017). "Regarded as the effectors of mi-RNA, targetgenes such as SP1, AR, and EGFR had the largest number of edges in the network, indicating that they were closely associated with other genes and played significant roles in stroke." (PMID 26830013, 2016). "Although the discussion was mainly focused on the gene SP1 that presented significant expression change in the case of stroke, other genes with minor expression variances may also worth a closer look, including PF4 (LFC: 0.79; p-value< 10–3), CYP4V2(LFC: 0.72; p-value = 0.046)." (PMID 33092540, 2020).
Stroke (continued). "Collectively, the results of the present study suggest that stroke induced an increase in HDAC9 in the cytosol of neurons activating the pro-ferroptotic pathway HIF-1/TfR1 and reduces the anti-ferroptotic pathway Sp1/GPX4." (PMID 37324938, 2023). "We investigated the possible interaction between HDAC9 and transcriptional factors involved in stroke pathophysiology, that are able to activate in a sequence specific manner their target genes TfR1 22 and GPX4 26, such as HIF-1 and Sp1 in SH-SY5Y cells after OGD/Rx." (PMID 37324938, 2023). "Results showed that the pathways where SP1 promoting stroke-inhibitors were activated, while the ones where SP1 inhibiting stroke-promoters pathways were not." (PMID 33092540, 2020). "Next we asked whether the inhibition of Sp1 with MitA could restore normal vascular contractile function by preventing the increase in ETBR-mediated vasoconstriction after in vivo; stroke and in vitro; organ culture." (PMID 25479176, 2014). "We further revealed that transcription factor sp1 is able to regulate CIRP expression in ischemic neurons and CIRP may promote NETs formation in tMCAO mice via the TLR4/p38 signaling pathway, which may also provide insights into stroke treatment." (PMID 38377019, 2024). "Furthermore, silencing of HDAC9 also prevented HIF-1 increase, Sp1 decrease, and consequently, the modulation of their target genes TfR1 and GPX4 in neurons in in vitro and in vivo models of stroke as demonstrated by Western blot and immunohistochemistry experiments." (PMID 37324938, 2023). "Interestingly, SP1 is expressed in HT22 cells and stroke-induced mice." (PMID 28596967, 2017). "Though there is a lack of evidence on the correlation between SP1 and EGFR via MAPK cascade in stroke in published literatures, a proper inference could be made in our study." (PMID 26830013, 2016).
breast tumor (8 papers, 2004 to 2022). "In support of our results, Nam and colleagues similarly reported a strong decreased expression of Sp1 after CD44 silencing in MDA-MB-231 and Hs578T breast tumor cells, that was associated with decreased migratory/invasive properties." (PMID 35805061, 2022). "Single hyper methylation of CpG island in the promoter region of miR-34c gene repressed miR-34c expression by reducing DNA binding activities of Sp1 and promoted self-renewal and epithelial-mesenchymal transition of breast tumor-initiating cells." (PMID 26975503, 2016). "Here, we identify the SP1 transcription factor as an essential mediator of RhoU transcriptional activation downstream of the WNT/PCP pathway, and we unveil a functional cooperation between WNT/PCP/JNK1, RHOU, SP1 and STAT3 to promote cell motility in basal-like human breast tumor cells." (PMID 30654518, 2019).
endometrial cancer (8 papers, 2016 to 2024). Primary or metastatic malignant neoplasm involving the endometrium (mucous membrane that lines the endometrial cavity). "mRNA levels were evaluated after knock-down of SNHG4 in two endometrial cancer cell lines, and it was confirmed that the expression of E-cadherin increased and, conversely, the expression of β-catenin, N-cadherin, SP-1, and Wnt5β decreased." (PMID 37189636, 2023). "In summary, these data demonstrate that in endometrial cancer, SNHG4 is regulated by SP-1 at the transcriptional level and is indirectly associated with SNHG4." (PMID 37189636, 2023). "It was confirmed that the expression of E-cadherin increased in the two cells of endometrial cancer and, on the contrary, the protein expression of β-catenin, N-cadherin, SP-1, and Wnt5β decreased." (PMID 37189636, 2023). "In order to confirm the effect of SP-1 on endometrial cancer cells, siSP-1 was transfected in two cell lines and knocked down, and two siRNAs (Nos." (PMID 37189636, 2023). "Next, expression of SP-1 was confirmed in the endometrial cancer cell lines ECC1 and Ishikawa." (PMID 37189636, 2023). "We found in this study that SNHG4/SP-1 plays an important role in endometrial cancer progression and may be used as a potential therapeutic and prognostic biomarker for endometrial cancer." (PMID 37189636, 2023). "Sp1 negatively regulated TPX2 expression, affecting the malignant progression of endometrial cancer cells by coupling the CX3CR1/CXCL10 chemokine pathway to the PI3K/Akt signaling pathway." (PMID 38466034, 2024). "Sp1 regulates TPX2 expression, resulting in a cascade effect, in EC; it affects the malignant progression of endometrial cancer cells by coupling the CX3CR1/CXCL10 chemokine pathway to the PI3K/Akt signaling pathway." (PMID 38466034, 2024). "In this study, we investigated the anticancer properties of lncRNA SNHG4 in endometrial cancer cells and confirmed that SNHG4 knock-down inhibited EMT and SP-1, thereby inhibiting cell migration and invasion." (PMID 37189636, 2023). "Next, we confirmed the relationship between SP-1 and EMT because SP-1 also affected migration and invasion in endometrial cancer." (PMID 37189636, 2023). "Knockdown of LSR significantly induces Sp1 transcription factor activity in the CLDN-1 promoter region and promotes cell invasion via CLDN-1-mediated MMPs in endometrial cancer cells." (PMID 36961882, 2023). "While in endometrial cancer, DLEU1 regulates SP1 expression via sponging miR-490 and aggravates the cancer development." (PMID 34113562, 2021). "Additionally, to evaluate the relationship between SP-1 and SNHG4, one of the transcription factors regulating lncRNA, the expression of SP-1 was evaluated in endometrial cancer cells in which SNHG4 was knocked down, and it was confirmed that the expression of SP-1 was reduced." (PMID 37189636, 2023). "Thus, SNHG4 may contribute to the endometrial cancer cell phenotype through activation of EMT and SP-1 signaling." (PMID 37189636, 2023).
endometriosis (8 papers, 2014 to 2025). The growth of functional endometrial tissue in anatomic sites outside the uterine body. "Investigators have found that SP1 mRNA and protein are highly expressed in the ectopic endometrium compared with the normal endometrium, thus verifying that in endometriosis SP1 is upregulated." (PMID 39982662, 2025). "We used quantitative real-time polymerase chain reaction (qRT-PCR) to study mRNA expression levels of TF, PAR-2, VEGF, and SP1 in endometriotic tissues of women who underwent surgery for endometriosis and received GnRH-a (leuprolide acetate) preoperatively." (PMID 38639888, 2024). "This miRNA is down-regulated in endometriosis and targets SP1, a transcription factor involved in the pathogenesis of endometriosis and estrogen metabolism." (PMID 38999962, 2024). "Therefore, supplementary treatments that affect the SP1 pathway of angiogenesis should be developed to enhance the antiangiogenetic effect of GnRH-a in patients with endometriosis." (PMID 38639888, 2024). "However, the expression and role of Sp1 in endometriosis remains unknown." (PMID 39982662, 2025). "In a recent study, SP1 mRNA and protein levels were found to be increased in ectopic and eutopic endometrium of women with stage III/IV endometriosis." (PMID 38639888, 2024).
heart failure (8 papers, 2018 to 2024). Inability of the heart to pump blood at an adequate rate to meet tissue metabolic requirements. "Then, a marked decrease in miR-665 level was accompanied with si-Sp1, further suggesting that the overexpression of miR-665 in heart failure is induced by Sp1." (PMID 30243022, 2018). "Since the transcription factor specificity protein 1 (Sp1) is involved in TGF-β1-stimulated alpha 2(I)-collagen transcription, and connective tissue growth factor (CTGF) participates in the regulation of cardiac fibrosis and heart failure, we examined the induction of SP1 and CTGF by I/R injury." (PMID 33578994, 2021). "Western blotting showed cardiac Sp1 protein level was increased in TAC-induced heart failure mice." (PMID 30243022, 2018). "This has been confirmed in a porcine model of heart failure, where administration of AAV1-SUMO1 increased specificity protein-1 (Sp-1) SUMOylation, improving cardiac function and stabilisation of LV volumes." (PMID 34076247, 2021). "Sp1 participated in TGF-β1-stimulated alpha 2(I)-collagen transcription, and CTGF was involved in the regulation of cardiac fibrosis and heart failure." (PMID 32354131, 2020). "Therefore, increased Sp1 in TAC-induced heart failure mice may lead to an increase of miR-665, then reduce CD34 level, finally aggravate heart failure." (PMID 30243022, 2018). "Moreover, a model was used to illustrate the roles of Sp1, miR-665 and CD34 in heart failure." (PMID 30243022, 2018).